ENSG00000257062 (novel transcript)
Gene: Protein-coding gene on chromosome 12 (21,047,179 to 21,176,895, forward strand). Ensembl gene ENSG00000257062.
Genetic constraint (gnomAD): Missense variants: 59 observed, 44.57 expected, observed/expected ratio (o/e) 1.32, 90% interval 1.07 to 1.64. Synonymous variants: 23 observed, 17 expected, observed/expected ratio (o/e) 1.35, 90% interval 0.97 to 1.84.